AIF1 (allograft inflammatory factor 1)
Diseases named in the same sentence as AIF1 in open-access papers (continued):
Sharing a sentence is not in itself a finding about the gene and the disease.
osteosarcoma (2 papers, 2024). A usually aggressive malignant bone-forming mesenchymal neoplasm, predominantly affecting adolescents and young adults. "Taking the phenomenon above, we suspected that activation of AIF1 is associated with a better prognosis in osteosarcoma patients." (PMID 38521928, 2024). "This is the first study to report the association between AIF1 expression and the clinical pathological features of osteosarcoma." (PMID 38521928, 2024). "In conclusion, we demonstrated that AIF1 functions as a tumor suppressor, and loss of AIF1 expression may represent a novel indicator for the progression and prognosis of osteosarcoma." (PMID 38521928, 2024). "Our data demonstrated that AIF1 functions as a tumor suppressor, and loss of AIF1 expression may represent a novel indicator for the progression and prognosis of osteosarcoma." (PMID 38521928, 2024). "In summary, we found that AIF1 is related to the immunity of osteosarcoma, affects the immune-related pathway, and inhibits the occurrence and development of osteosarcoma by inhibiting the NF-kappa B signaling pathway." (PMID 38521928, 2024). "Taken together, we can conclude that the NF-κB pathway plays an important role in AIF1-mediated proliferation, migration, and invasion of osteosarcoma cells." (PMID 38521928, 2024). "First, we found that AIF1 was lowly expressed in osteosarcoma cell lines, especially in 143B and U2OS cells." (PMID 38521928, 2024). "These enrichment results suggest that AIF1 can regulate the immune microenvironment of osteosarcoma patients, and thus play an important role in the development of osteosarcoma." (PMID 38521928, 2024). "To study the effect of AIF1 on the proliferation of osteosarcoma cells, we increased the expression of AIF1 in 143B and U2OS cells." (PMID 38521928, 2024). "We aimed to investigate the potential biomarker, allograft inflammatory factor-1 (AIF1), affecting the progression and prognosis of osteosarcoma." (PMID 38521928, 2024). "In the transwell assay, AIF1 overexpression significantly decreased the invasive ability of osteosarcoma cells." (PMID 38521928, 2024). "Taken together, our results suggested that overexpression of AIF1 restrained the proliferation, migration, and invasion of osteosarcoma cells." (PMID 38521928, 2024). "These functional enrichment results further confirm the key role of AIF1 in the immunity of osteosarcoma." (PMID 38521928, 2024). "So, we further performed in vitro experiments to elaborate on the potential roles of AIF1 in proliferative and invasion ability and the influence in the NF-κB pathway of osteosarcoma cells." (PMID 38521928, 2024). "The results showed that the expression of AIF1 in these osteosarcoma cells was significantly decreased." (PMID 38521928, 2024). "Cell experiments showed that AIF1 was underexpressed in osteosarcoma cell lines, while the malignant propriety was attenuated after overexpressing the expression of AIF1." (PMID 38521928, 2024). "GO and KEGG enrichment analysis of differential genes showed that AIF1 was closely related to the immune and NF-kappa B signaling pathways of osteosarcoma." (PMID 38521928, 2024). "Analysis of immune infiltration in patients with osteosarcoma showed that AIF1 can affect the expression of many immune cells and immune functions." (PMID 38521928, 2024). "GSEA and ssGSEA analysis showed that AIF1 affected the immune microenvironment of osteosarcoma and was correlated with immune checkpoints." (PMID 38521928, 2024). "We further performed a set of cell function experiments to investigate whether AIF1 overexpression can inhibit the migration and invasion of osteosarcoma." (PMID 38521928, 2024). "In summary, AIF1 can affect the immune cells and immune microenvironment of osteosarcoma patients, and then affect the occurrence and development of osteosarcoma and the prognosis of osteosarcoma patients." (PMID 38521928, 2024).
osteosarcoma (continued). "According to the expression level of AIF1, osteosarcoma patients in TCGA were divided into high- and low-expression groups, and then differential genes between the two groups could be obtained." (PMID 38521928, 2024). "Moreover, IHC results suggested a higher AIF1 level in the normal tissue than that in the osteosarcoma tissue." (PMID 38521928, 2024). "In the present study, we explored a potential prognostic biomarker, AIF1, of osteosarcoma." (PMID 38521928, 2024). "Osteosarcoma patients with high expression of AIF1 alteration showed better overall survival and metastasis-free survival; while the other hub genes showed no significance with either overall survival or metastasis-free survival of osteosarcoma patients." (PMID 38521928, 2024). "Combining these studies and our results, we found that AIF1 may be an osteosarcoma guardian gene and may serve as a protective prognostic indicator." (PMID 38521928, 2024). "However, the specific mechanisms by which AIF1 inhibits tumor action by inhibiting the NF-kappa B signaling pathway, and whether AIF1 is beneficial as a future prevention and treatment target for osteosarcoma, remain to be further investigated." (PMID 38521928, 2024). "However, it has not yet been reported whether AIF1 is also associated with the development of osteosarcoma." (PMID 38521928, 2024). "Therefore, the study of AIF1 may bring progress in the treatment of osteosarcoma patients." (PMID 38521928, 2024).
parasitic infections (2 papers, 2020 to 2021). "However, AIF1 involvement in monocyte and macrophage functions during parasitic infections has not been explored." (PMID 33441583, 2021).
pneumonia (2 papers, 2023 to 2024). An acute, acute and chronic, or chronic inflammation focally or diffusely affecting the lung parenchyma, caused by an infection in one or both of the lungs (by bacteria, viruses, fungi, or mycoplasma.). "Finally, on day 14, only single AIF1-positive cells were found perivascularly, even in areas that showed a prominent thickening of the interstitium, which is indicative of previous pneumonia." (PMID 38009950, 2024).
thyroid cancer (2 papers, 2021 to 2023). "In addition, we observed a significant correlation between the expression of AIF-1 and various types of infiltrating immune cells, including CD8+ T cells, CD4+ T cells, B cells, macrophages, NK cells, and dendritic cells in both thymic carcinoma (THYM) and thyroid carcinoma (THCA)." (PMID 37014322, 2023).
uremia (2 papers, 2020 to 2023). A clinical syndrome associated with the retention of renal waste products or uremic toxins in the blood. "For the first time, we have demonstrated that the crosstalk between calcium ions and aldosterone contributes to the inflammation, apoptosis, and calcification of VSMC via the AIF-1/NF-κB pathway in uremia." (PMID 33343805, 2020). "These in vivo and in vitro results suggest that the crosstalk between calcium ions and aldosterone plays an important role in VSMC calcification in uremia via the AIF-1/NF-κB pathway." (PMID 33343805, 2020). "This study shows that the crosstalk between calcium and aldosterone via the allograft inflammatory factor 1 (AIF-1) pathway contributes to calcium homeostasis and VSMC calcification, which is a novel mechanism of vascular calcification in uremia." (PMID 33343805, 2020).
abscess (1 paper, 2018). An inflammatory process characterized by the accumulation of pus within a newly formed tissue cavity which is the result of a bacterial, fungal, or parasitic infection or the presence of a foreign body. "GO analysis with the unique differential promoters involved in Munro’s abscess formation revealed neutrophil and leukocyte chemotaxis as the highest enriched biological processes which include genes like HRH1, PDE4D, CCL25, AIF1, ADAM10, FFAR2, IL1B and TREM1." (PMID 30092825, 2018).
alcohol addiction (1 paper, 2022). "These alterations were accompanied by an increase of glial fibrillary acidic protein (GFAP) and allograft inflammatory factor 1 (AIF-1) in the medial prefrontal cortex (mPFC) and HIP, respectively, crucial brain areas for the development of alcohol addiction." (PMID 35682586, 2022).
anterior uveitis (1 paper, 2024). Inflammation of the iris and anterior chamber of the eye. "In summary, our study revealed that differentiation of myeloid cells into DCs and downregulation of AIF1 within cDCs play pivotal roles in the acute pathogenesis of SpA/HLA-B27-associated anterior uveitis." (PMID 38475831, 2024). "Mendelian randomization analysis revealed that circulating levels of AIF1 and VARS were significantly associated with a reduced risk of developing SpA/HLA-B27-associated AAU, with AIF1 showing a robust correlation with anterior uveitis onset." (PMID 38475831, 2024).
calcification (1 paper, 2022). Process by which organic tissue becomes hardened by the physiologic deposit of calcium salts. "Suggesting that the role of AIF-1 in vascular calcification in CKD may be related to the NF-κB signaling pathway." (PMID 35937793, 2022). "In addition, AIF-1 could mediate elevations in serum phosphorus, FGF23, PTH, and vascular CCR2 as demonstrated in the present study, which was previously thought to be pathways of NF-κB causing vascular calcification." (PMID 35937793, 2022).
cerebral aneurysms (1 paper, 2024). "Overall, our findings suggest that CCDC90B, tRNA PusA, and MRM3 may be common risk factors for cerebral aneurysms (ruptured and unruptured), while AIF1 and NAGS are specifically associated with an increased risk of aSAH, unrelated to uIA." (PMID 39087007, 2024). "The results suggest that CCDC90B, tRNA PusA, and MRM3 may be common risk factors for cerebral aneurysms (ruptured and unruptured), while AIF1 and NAGS are specifically associated with an increased risk of aSAH, unrelated to uIA." (PMID 39087007, 2024). "In line with our research findings, AIF1 may be a significant factor contributing to cerebral aneurysms, particularly aSAH." (PMID 39087007, 2024).
cervical cancer (1 paper, 2022). A primary or metastatic malignant neoplasm involving the cervix. "Furthermore, lymph node involvement was associated with an elevated serum level of AIF-1 in patients with cervical cancer, supporting the proposal that AIF-1 may be a marker of more aggressive tumor behavior." (PMID 36520870, 2022).
coronary heart disease (1 paper, 2023). "Immunohistochemical staining of AIF1 in artery segments with atherosclerotic plaques from coronary heart disease patients showed high positive staining of AIF1 in the tunica intima and media, and positive AIF1 staining was not present in the artery segments without atherosclerotic plaques." (PMID 37237507, 2023).
cryptococcosis (1 paper, 2011). An acute or chronic, localized or disseminated infection by Cryptococcus neoformans. "To test if that would also be the case for isolates in the aif1 mutant background, we tested the virulence of two strains completely resistant to FLC using an inhalation murine model of cryptococcosis." (PMID 22114551, 2011).
diffuse large B-cell lymphoma (1 paper, 2023). "The findings of this study demonstrated that alterations in AIF-1 were not ubiquitous, with the most frequently affected cancer type being lymphoid neoplasm diffuse large B-cell lymphoma (DLBC), with over 8% of DLBC patients exhibiting alterations, mainly in the form of deep deletions." (PMID 37014322, 2023).
Graves disease (1 paper, 2025). Graves' disease is an autoimmune disorder that leads to overactivity of the thyroid gland (hyperthyroidism).It is caused by an abnormal immune system response that causes the thyroid gland to produce too much thyroid hormones. "XIST, PPP1R2C, CALHM6, AL672277.1, TSIX, SHROOM1, ADTRP, JUND, SGK1, CHKA, AO008569.1, MAP7D2, and AIF1 were down-expressed genes in TS compared with both the healthy female and the female patient with Graves’ disease." (PMID 39851522, 2025).
IgA nephropathy (1 paper, 2024). "We found that Apo A-IV, HLA-E, and AIF1 were negatively associated with IgA nephropathy; however, HLA-E and AIF1 were positively associated with other CKD types." (PMID 38898508, 2024).
iridocyclitis (1 paper, 2024). "Lastly, 3 plasma proteins share the same genetic variant with chronic iridocyclitis: AIF1 (coloc.abf-PPH4 = 1.000), AGER (coloc.abf-PPH4 = 0.887), and COL11A2 (coloc.abf-PPH4 = 0.872)." (PMID 38475831, 2024). "Two proteins that are causally associated with AS and iridocyclitis are AIF1 and VARS, and AIF1 is causally associated with only acute and subacute iridocyclitis." (PMID 38475831, 2024). "Two proteins, AIF1 (OR = 0.52; 95% CI 0.40–0.67; P = 5.35 × 10–7) and ENTPD5 (OR = 0.79; 95% CI 0.71–0.89; P = 2.56 × 10–5), were causally associated with chronic iridocyclitis." (PMID 38475831, 2024).
laryngeal squamous cell carcinoma (1 paper, 2022). A squamous cell carcinoma that arises from the larynx. "In a genome-wide association study involving 993 laryngeal squamous cell carcinoma patients and 1,995 controls, researchers found the three most significant SNPs—rs174549, rs2857595, and rs10492336—which are located in FASD1, AIF1, and TBX5 genes, respectively." (PMID 35530357, 2022).
lymph node metastasis (1 paper, 2022). "We also found that the AIF-1 expression level in NSCLC tissue was positively associated with malignant characteristics such as lymph node metastasis, and TNM stage." (PMID 36520870, 2022).
malnutrition (1 paper, 2022). Inadequate nutrition resulting from poor diet, malabsorption, or abnormal nutrient distribution. "When injury or inflammation occurs, astrocytes induce GFAP expression, while microglia favor the expression of allograft inflammatory factor 1 (AIF-1), to counteract the neuronal damage caused by inflammation resulting from malnutrition." (PMID 36290695, 2022).
membranous nephropathy (1 paper, 2024). "In addition, we observed that BTN3A2, BTN3A3, and MICB decreased the risk of membranous nephropathy, but sRAGE and AIF1 increased this risk." (PMID 38898508, 2024).
morbid obesity (1 paper, 2013). An excess of body weight, normally defined as an individual with a body mass index greater than 35 or a body weight greater than one hundred percent of ideal body weight. "Of these, AIF1 was originally reported as a weight locus and the PTER and MAF as loci for morbid obesity." (PMID 23861046, 2013).
myocardial ischemia (1 paper, 2023). A disorder of cardiac function caused by insufficient blood flow to the muscle tissue of the heart. "Eight genes (Aif1, Apoe, Arg1, Col1a1, Gpx7, Hmox1, Mmp14, and Sirpa) were significantly differentially expressed in the rat myocardial ischemia-reperfusion model." (PMID 36826575, 2023).
nasal polyps (1 paper, 2022). "Among these genes, PLEK was reported to be involved in CRSwNP but not correlated with M2 macrophages while AIF1, CD53 and LAPTM5 were related to M2 macrophages but not explored in nasal polyps." (PMID 36466903, 2022).
nephritis (1 paper, 2018). Inflammation of renal tissue. "These authors could also show a pronounced upregulation of AIF1 in the glomerular compartment in an inflammatory model (anti-GBM nephritis model), although the main source was identified to be intruding inflammatory cells." (PMID 30001384, 2018).
ovarian carcinoma (1 paper, 2025). A malignant neoplasm originating from the surface ovarian epithelium. "In ovarian cancer, BRCA1-mut cancer genes such as AIF1, CD8A, and BST1 showed detrimental prognosis, while in BRCA2-mut ovarian cancer, SEC61A2 and IGFBP3 were associated with shorter survival." (PMID 40647506, 2025). "These include AIF1, CD8A, and BST1 in ovarian cancer BRCA1-mutant cancers, and SEC61A2 and IGFBP3 in BRCA2-mutant ovarian cancer." (PMID 40647506, 2025).
pancreatic cancer (1 paper, 2024). "Finally, our analysis of inflammatory biomarkers shows that AIF-1, IL-12A and IL-18 are directly related to pancreatic cancer mortality, whereas IL-10 shows an inverse association." (PMID 38785507, 2024).
psoriasis (1 paper, 2024). An autoimmune condition characterized by red, well-delineated plaques with silvery scales that are usually on the extensor surfaces and scalp. "AIF1, another potential target of psoriasis, is a Ca2+-binding EF-hand cytokine encoded in the major histocompatibility complex III region on chromosome 6." (PMID 39883516, 2024). "Consistent with published findings, our study provided further evidence that AIF1 was associated with psoriasis." (PMID 39883516, 2024). "This study announced that AIF1, FCGR3, and HSPA1A were the unexplored but material variants of psoriasis, thus providing novel and valuable targets for psoriasis treatment and broadening new orientation of drug development for psoriasis." (PMID 39883516, 2024). "Based on the GWAS data, further MR analysis and colocalization analysis genetically predicted that AIF1, FCGR3A, NEU1, HSPA1A, TNXB (Tenascin XB), and ABO were associated with psoriasis risk." (PMID 39883516, 2024). "Among these proteins, AIF1, FCGR3A (Fc gamma receptor IIIa), and NEU1 (neuraminidase 1) were considered the strongest candidates for psoriasis risk (PP.H4 = 1)." (PMID 39883516, 2024). "In the PPI network analysis, TNF, a known target of psoriasis, is strongly correlated with AIF1." (PMID 39883516, 2024). "MR analyses unveiled 19 unique circulating proteins that were associated with psoriasis, among which only AIF1, FCGR3A, NEU1, HSPA1A, TNXB, and ABO were the potential proteins that interacted with psoriasis risk after being analyzed with high evidence of colocalization (PP.H4 > 0.9)." (PMID 39883516, 2024). "A previous study showed that AIF1 was upregulated in psoriasis patients." (PMID 39883516, 2024). "Together, AIF1 functions as one reliable target for psoriasis." (PMID 39883516, 2024). "Combined with the protein target druggability, mouse KO models, and PPI network, FCGR3A, AIF1, and HSPA1A were highlighted for functioning as potential targets for psoriasis with strong evidence." (PMID 39883516, 2024). "AIF1 (allograft inflammatory factor 1), FCGR3, and HSPA1A [shock protein family A (Hsp70) member 1A] were finally identified as novel and valuable targets for psoriasis treatment, broadening new possible orientations of drug development for psoriasis." (PMID 39883516, 2024). "In addition, AIF1, FCGR3A, and HSPA1A have been finally determined to be feasible therapeutic targets for psoriasis after being confirmed by druggability verification and specific mouse knock-out models." (PMID 39883516, 2024).
pulmonary fibrosis (1 paper, 2022). Chronic progressive interstitial lung disorder characterized by the replacement of the lung tissue by connective tissue, leading to progressive dyspnea, respiratory failure, or right heart failure. "C1qa, Fcgr1, C1qb, C1qc, Ccr5, Slc11a1, Aif1, Emr1 and Cxcl10 were identified as the most closely connected module which were highlighted in yellow, including 9 nodes and 32 edges, and the genes in this region were upregulated in pulmonary fibrosis." (PMID 35078421, 2022).
reactive arthropathies (1 paper, 2024). "Our analysis revealed a significant causal relationship between AIF1 and reactive arthropathies (OR = 0.66; 95% CI 0.55–0.80; P = 1.20 × 10−5)." (PMID 38475831, 2024).
renal cell carcinoma (1 paper, 2023). "Second, this study presents the role of AIF-1 in various cancers through bioinformatics analysis, is validated by clinical specimens from KIRC, and uses a renal cell carcinoma cell line to perform functional cell testing in vitro." (PMID 37014322, 2023). "Of equal importance, we carried out a series of experiments to investigate the expression of AIF-1 in KIRC tissues and renal cell carcinoma (RCC) cells." (PMID 37014322, 2023).
rheumatic diseases (1 paper, 2025). "It has been discovered that some of these genes (C2, BX511262.2, PRRC2A, BAG6, PBX2, GPSM3, NELFE and AIF1) are significant genetic targets shared by MetS and multiple rheumatic diseases." (PMID 39789419, 2025).